PIK3CA (phosphatidylinositol-4,5-bisphosphate 3-kinase catalytic subunit alpha)
Diseases named in the same sentence as PIK3CA in open-access papers (continued):
Sharing a sentence is not in itself a finding about the gene and the disease.
breast cancer (continued). "HER2-positive breast cancer with activating mutations of PIK3CA do not respond to trastuzumab treatment." (PMID 26469692, 2015). "Improvements can be expected by addressing key features of HER2-positive breast cancer linked to different sensitivity in term of hormone receptor status (positive versus negative), PIK3CA status (wild type versus mutant), and immune environment." (PMID 25374620, 2014). "However, recent early results using the p110α isoform-selectiveinhibitors look promising in heavily pretreated PIK3CA mutant breast cancers." (PMID 25192370, 2014). "Activating mutations in PIK3CA, affecting the PI3K-AKT-mTOR pathway, are frequent in breast cancer and raise the question of whether they alter the balance of pathway utilization." (PMID 25170609, 2014). "This hypothesis is supported by data in breast cancer, which show little predictive value of PIK3CA with the mTOR inhibitor everolimus." (PMID 24777052, 2014). "Also of note is that the common breast cancer cell lines used inpreclinical experiments (MCF7 and T47D) contain a PIK3CA mutation (helicaland kinase domains, respectively)." (PMID 25192370, 2014). "In the studies from Buttitta and Barbareschi, patients with lobular breast cancer had more often PIK3CA exon 9 mutated tumors compared with nonlobular breast cancer." (PMID 24467828, 2014). "We found that PTEN mRNA levels do not correlate with PIK3CA mutations in ER+ breast cancer, suggesting that the contribution of decreased PTEN to activation of PI3K signaling is independent of PIK3CA mutations." (PMID 25212826, 2014). "However, in breast cancer cells with mutant PIK3CA, a well-known downstream target of EGFR signaling, knockdown of flotillin-1 causes an upregulation of EGFR and hyperactivation of MAPK signaling." (PMID 25180832, 2014). "PIK3CA mutations are frequent in EC and CCC, as well as endometrial and breast cancers." (PMID 24559118, 2014). "PTEN loss (by IHC) and PIK3CA mutations are reported not to be mutually exclusive in breast cancers, suggesting that they have different contributions to tumor pathophysiology and pathway activation." (PMID 25212826, 2014). "Our results indicate that PIK3CA mutations are unlikely to have important clinical validity to predict adjuvant tamoxifen resistance in postmenopausal breast cancer patients." (PMID 24467828, 2014). "Several different types of Pik3ca-driven mouse models of breast cancer havebeen reported." (PMID 25192370, 2014). "In some breast cancer cases, mutations at certain components of this pathway (e.g., PIK3CA) are associated with a better prognosis than breast cancers lacking these mutations." (PMID 25051360, 2014). "Altogether, our data indicate that in ERα-positive postmenopausal breast cancer patients, PIK3CA mutations are not enriched in lobular breast cancer, but are associated with favorable prognostic factors like low grade and positive PgR status." (PMID 24467828, 2014). "PIK3CA, on the other hand, is commonly mutated in both early neoplasias (approximately 50%) and ER+/luminal breast cancers (approximately 20%) but does not show significant expression changes in the early neoplasias." (PMID 24887547, 2014). "Verification of tumor cell identity for single cells isolated by DEPArray from spiking experiments using the SW480 colon carcinoma cell line and the MCF-7 breast cancer cell line was achieved by sequencing of the known KRAS (G12V) and PIK3CA (E545K) mutations, respectively." (PMID 25133137, 2014).
breast cancer (continued). "To model the oncogenic PIK3CA-driven early stages of cancer, we used the clonal breast cancer cell line MCF10DCIS.com, which harbors the gain-of-function H1047R hot-spot mutation in the catalytic domain of the PI3KCA gene and has been shown to form DR-refractory xenotumors." (PMID 23986086, 2013). "PIK3CA mutations and PIK3R1 underexpression show opposite effects on patient outcome and could become useful prognostic and predictive factors in breast cancer." (PMID 24229379, 2013). "There is growing evidence supporting PIK3CA mutations as good prognostic markers in breast cancer, but the negative impact of PIK3R1 underexpression on patient survival has been less extensively studied." (PMID 24229379, 2013). "Furthermore, the current cohort of breast cancer cell lines contained 15 PIK3CA mutant cell lines (four ER-negative, eleven ER-positive) and eight PTEN mutant cell lines (four ER-negative, four ER-positive)." (PMID 23601657, 2013). "Since AZD5363 induces FoxO3a nuclear translocation in ER+/PIK3CA mutant breast cancer cells and ER mRNA in LTED cells, we examined whether knockdown of ER and/or FoxO3a affects AZD5363-induced transcription of IGF-IR, InsR, and IGF ligands." (PMID 23844554, 2013). "For example, breast cancer cells were found to be sensitive to growth inhibition by PI3K inhibitors without having mutations in PTEN or PIK3CA genes." (PMID 23459844, 2013). "Breast cancer patients with bone metastases may be candidates for treatment with selective PIK3CA inhibitors." (PMID 22970388, 2012). "Whereas PIK3CA mutations and HER2 amplification have been identified in the majority of preclinical breast cancer studies as determinant of sensitivity to PI3K pathway inhibition downstream of RTKs, the correlation between PTEN deficiency and response is less clear." (PMID 22970424, 2012). "Several studies have evaluated PIK3CA mutation status in breast cancer metastases, although none to date have looked specifically in bone metastases." (PMID 22970388, 2012). "PIK3CA mutations have also been detected in ductal carcinoma in situ (DCIS), a precursor of breast cancer, suggesting they may play a role in tumor initiation rather than progression." (PMID 22666336, 2012). "PIK3CA mutation and HER2 amplification have been recommended as useful biomarkers in breast cancer." (PMID 22662154, 2012). "Activating point mutations in the PIK3CA gene are common in primary breast cancer tumors, but their presence in breast cancer bone metastases has not been assessed previously.Results." (PMID 22970388, 2012). "To better understand the role of mutant PIK3CA in the initiation and/or progression of breast cancer, we have generated mice with a conditional knock-in of the common activating mutation, Pik3caH1047R, into one allele of the endogenous gene in the mammary gland." (PMID 22666336, 2012). "PI3K signaling appears to depend upon PDK1 rather than AKT in several breast cancer cell lines harboring the H1047R mutation in PIK3CA, and thus it remains to be seen if a similar mechanism exists in the L3.3 model." (PMID 22952903, 2012). "Furthermore, an association between PIK3CA mutation and resistance to Trastuzumab therapy in HER-2-amplified breast cancer cell lines has also been reported." (PMID 22935382, 2012). "In xenografts derived from the breast cancer cell line MCF7 and the pancreatic carcinoid cell line BON, both harboring an activating PIK3CA mutation, treatment with the allosteric mTOR inhibitor Rapamycin (Sirolimus) was associated with a significant decrease in tumor volume." (PMID 22970424, 2012). "Moreover, a knock-in PIK3CA H1047R mutant is sufficient to induce lung and breast cancer development." (PMID 22666248, 2012).
breast cancer (continued). "As RTK/PIK3CA/AKT1/PTEN and IKK/NFκB are the two most frequently mutated pathways in breast cancer, any crosstalk between them may represent a critical therapeutic target." (PMID 21646685, 2011). "PIK3CA mutations either do not occur, or occur at a very low frequency, in claudin-low breast cancer." (PMID 21646685, 2011). "NRIP3, TMC5, REEP1 and NKAIN1, whose expression had not previously been described in breast cancer, were also deregulated in the PIK3CA-mutated breast tumors." (PMID 21209903, 2010). "Moreover, introduction of the mutant PIK3CA gene was reported to enhance the migration, invasion, and metastasis of breast cancer cells." (PMID 21307399, 2010). "Despite these findings, a recent study demonstrated that a noncatalytic site Akt inhibitor was effective against breast cancer cell lines with PIK3CA mutations and HER2 amplifications." (PMID 21317449, 2010). "The fact that PIK3CA mutations and PTEN loss were nearly mutually exclusive implied that deregulated PI3K signaling is critical for tumorigenesis in breast cancers and that loss of either PIK3CA or PTEN abrogates the selective pressure for targeting of the other gene." (PMID 19384426, 2007). "Somatic mutation rather than a gain of gene copy number of PIK3CA is the frequent genetic alteration that contributes to human breast cancer progression." (PMID 16168105, 2005). "We further investigated the biological effects of PIK3CA mutation in breast cancer cell lines by treating breast cancer cells with or without PIK3CA mutation with the PIK3CA inhibitor LY294002." (PMID 16168105, 2005). "Even though PIK3CA amplification and somatic mutation have been reported previously in various kinds of human cancers, the genetic change in PIK3CA in human breast cancer has not been clearly identified." (PMID 16168105, 2005). "In addition, PIK3CA gene copy number was also determined in 12 breast cancer cell lines, and the MCF7, T47D, and BT474 cell lines had more than 4 copies." (PMID 16168105, 2005). "The results from this study indicate that somatic mutation rather than gene amplification of PIK3CA is the main genetic alternation in breast cancer." (PMID 16168105, 2005). "From both the U.S. and Chinese perspectives, the ICER for the inavolisib triple regimen is higher than the WTP threshold compared to palbociclib plus fulvestrant, making it not a cost-effective first-line treatment for PIK3CA-mutated HR+/HER2- advanced breast cancer." (PMID 41496420, 2026). "Luminal breast cancers are driven by estrogen signaling through ERα, which regulates genes involved in cell proliferation, while dysregulation of this pathway—particularly Via PI3K/AKT/mTOR activation due to PIK3CA mutations and PTEN loss—promotes tumor growth." (PMID 41002973, 2025). "Notably, PIK3CA mutations are frequently observed in HER2+ and ER+ breast cancer subtypes." (PMID 40303296, 2025). "In this study, we sought to compare the concordance of pathogenic alterations in PIK3CA, AKT1, AKT2, AKT3, and PTEN detected by tissue-based FoundationOne®CDx and blood-based FoundationOne®Liquid CDx in contemporaneous samples collected from patients with breast cancer." (PMID 40597213, 2025). "Due to activating mutations in PIK3CA and AKT1, and loss-of-function mutations in the tumor suppressor PTEN, it is frequently hyperactivated in triple-negative breast cancer, making this subtype of breast cancer particularly aggressive and resistant to conventional therapies." (PMID 40647529, 2025). "However, to further isolate the effect of tamoxifen on PIK3CA mutation frequencies, we also compared clinicogenomic TA-UCs with a unique cohort of de novo UC from patients with breast cancer never treated with tamoxifen." (PMID 40846762, 2025).
breast cancer (continued). "Collectively this suggests the AKT-FOXO3-FOXM1 axis plays a pivotal role in response to AKTi in ER+ breast cancer with PIK3CA mutations with and without expression of PTEN, that FOXO3 expression loss can mediate resistance, and that FOXM1 downregulation is a potential biomarker of response." (PMID 40263319, 2025). "Alpelisib, a selective phosphoinositide 3-kinase alpha (PI3Kα) inhibitor approved for hormone receptor-positive, HER2-negative, phosphatidylinositol-4,5-bisphosphate 3-kinase catalytic subunit alpha (PIK3Cα)-mutated breast cancer, is frequently associated with dermatologic adverse effects." (PMID 40868155, 2025). "Therefore, DMBA-induced mouse mammary tumors may serve as an excellent model to closely replicate the biology of PIK3CA-driven mammary carcinogenesis and to evaluate new PIK3CA/AKT/mTOR pathway inhibitory molecules in vivo." (PMID 40429718, 2025). "Based on these research findings, the NCCN Clinical Practice Guidelines for Breast Cancer 2025, Version 2, recommend alpelisib in combination with fulvestrant as the preferred second‐line treatment (Class 1) for postmenopausal breast cancer patients with HR‐positive/HER2‐negative PIK3CA mutations." (PMID 40206206, 2025). "Similarly, some gene alterations with matched therapies occurred at relatively higher frequencies in on-label cancer types, including alterations in PIK3CA (42.2% in on-label HR+/HER2- breast cancer vs. 10.6% in off-label cancers) and in EGFR (19.8% in on-label NSCLC vs. 0.1% in off-label cancers)." (PMID 40711866, 2025). "However, expression of catalytically active mutants of PIK3CA such as H1047R at physiological levels in mouse mammary tissue has failed to drive the development of breast cancer in the absence of accompanying mutations." (PMID 38987766, 2024). "Furthermore, the panel used in this study did not include the RB gene, which was thought to predict the efficacy of CDK4/6 inhibitors, or the ESR1 or PIK3CA genes, which were frequently observed in breast cancer and were considered involved in endocrine therapy resistance." (PMID 38539518, 2024). "Additionally, hsa-miR-152-3p may inhibit pathway activation by negatively regulating PIK3CA expression, thereby suppressing cell proliferation and functioning as a tumor suppressor in human breast cancer cells." (PMID 39169938, 2024). "Our findings justified that molecular subtype (HER2E and TNBC), biomarkers (ER, PR, HER2, HR, Ki-67, nm23-H1, CK5/6, and Tau), and gene (PIK3CA) could be further explored for their possible role in first-line treatment response in Asian breast cancer clinical studies." (PMID 38576013, 2024). "Additionally, research has shown that T-DM1 is active in PIK3CA-mutant breast cancer cell lines and xenograft models, likely due to its unique mechanism of action, which involves the HER2-mediated delivery of a chemotherapeutic payload, independent of downstream HER2 signaling." (PMID 39769140, 2024). "Recently, the FDA approved the Therascreen PIK3CA RGQ polymerase chain reaction assay as a companion diagnostic assay to detect PIK3CA mutations in breast cancer for both tissue and liquid biopsies, bringing the role of liquid biopsy into breast cancer management." (PMID 38869741, 2024).
breast cancer (continued). "Notably, despite the increase in PI3K pathway activity, and the frequent mutations in PIK3CA in breast cancer, there was no further increase in the PIK3CA mutation rate in metastases vs primary lesions." (PMID 37463901, 2023). "The animals that received DMBA administration showed PIK3CA gene mutations detected in all tumors, positively correlating with the activation of protein kinase B (AKT), and these genetic changes in the induced mammary tumors were similar to those that exist in natural mammary cancers." (PMID 36986040, 2023). "Not surprisingly, breast cancer was largely represented in our cohort of PIK3CA mutations." (PMID 36934165, 2023). "However, there is currently no canine cell line that specifically focuses on the novel breast cancer-associated mutational gene, PIK3CA." (PMID 38033642, 2023). "Furthermore, we investigated whether alpelisib, a PIK3CA inhibitor approved by the U.S. Food and Drug Administration for human breast cancer treatment, along with fulvestrant, is effective for CMT treatment." (PMID 38033642, 2023). "Phosphatidylinositol-4,5-bisphosphate 3-kinase catalytic subunit alpha (PIK3CA), encoding the p110α catalytic subunit of PI3K, as well as phosphatase and tensin homolog (PTEN), which are the suppressors of the PI3K/protein kinase B (Akt) signaling pathway, are frequently mutated in breast cancer." (PMID 36677797, 2023). "One patient with PIK3CA mutation was offered alpelisib, a PI3Kα-inhibitor indicated for the treatment of advanced breast cancer, but could not proceed with treatment due to clinical deterioration." (PMID 36959606, 2023). "We examined the hypothesis that PIK3CA mutations and low phosphatase and tensin homolog (PTEN) expression affect the response to neoadjuvant therapy and prognosis in postmenopausal luminal breast cancer patients." (PMID 37106324, 2023). "Among PI3Ki, alpelisib, a selective p110α inhibitor, is approved for the treatment of hormone receptor (HR)+/HER2- PIK3CA mutant metastatic breast cancer (BC) that has progressed to a first line endocrine therapy." (PMID 36579519, 2022). "In addition, breast cancer patients with high PIK3CA copy numbers have a worse prognosis." (PMID 35402264, 2022). "The Therascreen PIK3CA RGQ PCR Kit (Qiagen Gmbh, Hilden, Germany), which is based on real-time qualitative PCR, is used for the detection of 11 mutations in the PIK3CA gene in FFPE tumor DNA or ctDNA of patients with breast cancer to identify patients for targeted treatment with PIQRAY® (Alpelisib)." (PMID 35892331, 2022). "Finally, we measured the proportion of HLA-A LOH events in HLA-A*03:01+/WT PIK3CA breast cancers." (PMID 35484264, 2022). "We reviewed charts of patients diagnosed with metastatic, hormone receptor-positive, human epidermal growth factor receptor 2 negative, PIK3CA-mutated breast cancer treated with alpelisib from May 2019 to January 2022." (PMID 36338738, 2022). "Here, we detected activating PIK3CA mutations, AKT1 mutations, and inactivating PTEN alterations in 76 (54%) of an intention-to-treat population of postmenopausal women with ER-positive, HER2-negative advanced breast cancer who had previously been treated with an aromatase inhibitor." (PMID 35671774, 2022). "Importantly, PIK3CA genetic testing and the use of Alpelisib for HR + /HER2- breast cancer patients with PIK3CA mutation have been included in the National Comprehensive Cancer Network (NCCN) breast cancer clinical practice guidelines." (PMID 35778737, 2022). "PIK3CA molecular testing has rapidly emerged as a new clinical request at the sight of data from the SOLAR-1 study regarding the efficacy of alpelisib in combination with fulvestrant in patients with advanced HR+/HER2− breast cancer previously treated with endocrine therapy." (PMID 36428975, 2022).